RNU6-1061P (RNA, U6 small nuclear 1061, pseudogene)
Gene: Small nuclear RNA gene on chromosome 16 (71,563,430 to 71,563,528, reverse strand). Ensembl gene ENSG00000252339.
Homologues: Orthologues: chimpanzee U6 (99% identical), guinea pig U6 (60% identical), dog U6 (58% identical), rat LOC120094408 (58% identical), mouse Gm27449 (51% identical). Paralogues in human: RNU6-1304P (72% identical), RNU6-247P (71% identical), RNU6-537P (71% identical), RNU6-952P (71% identical), RNU6-104P (70% identical), RNU6-1219P (70% identical), RNU6-20P (70% identical), RNU6-333P (70% identical), RNU6-411P (70% identical), RNU6-428P (70% identical), RNU6-684P (70% identical), RNU6-921P (70% identical), and 1285 more.